NOAZFP (nucleolar atypical zinc finger)
Synonyms: ZNF330; NOA36; HSA6591
Tractability: PROTAC: ubiquitination databases record sites on it; its protein half-life has been measured.
Gene: Protein-coding gene on chromosome 4 (141,220,280 to 141,234,697, forward strand). Ensembl gene ENSG00000109445.
Subcellular location: Nucleus; Nucleus, nucleolus; Chromosome, centromere
Subcellular location (Human Protein Atlas): Nucleoli; Basal body; Centrosome; Cytosol; Plasma membrane; Primary cilium
Gene Ontology:
Molecular function: protein binding; metal ion binding; zinc ion binding
Cellular component: chromosome, centromeric region; midbody; nucleolus; nucleus
Genetic constraint (gnomAD): Loss-of-function variants: 27 observed, 38.68 expected, observed/expected ratio (o/e) 0.7, 90% interval 0.51 to 0.96. The upper end of that interval is the gene's LOEUF score, 0.96, which puts it in group 4 of 6, group 1 being the genes least tolerant of losing a copy. Missense variants: 326 observed, 361.73 expected, observed/expected ratio (o/e) 0.9, 90% interval 0.82 to 0.99. Synonymous variants: 130 observed, 117.44 expected, observed/expected ratio (o/e) 1.11, 90% interval 0.96 to 1.28.
Homologues: Orthologues: chimpanzee ZNF330 (100% identical), macaque ZNF330 (99% identical), rabbit ZNF330 (98% identical), dog ZNF330 (97% identical), pig ZNF330 (97% identical), rat Zfp330 (96% identical), guinea pig ZNF330 (95% identical), mouse Zfp330 (95% identical), tropical clawed frog znf330 (83% identical), zebrafish znf330 (72% identical), Drosophila melanogaster Noa36 (58% identical).
Diseases named in the same sentence as NOAZFP in open-access papers:
NOAZFP is named in the same sentence as 5 diseases in open-access papers, as found by Europe PMC text mining. Sharing a sentence is not in itself a finding about the gene and the disease.
NOAZFP shares sentences with these, for which no sentence is quoted: tumor (2 papers); breast carcinoma (1); cervical cancer (1); diabetes (1); infection (1).